IL6 (interleukin 6)
Diseases named in the same sentence as IL6 in open-access papers (continued):
Sharing a sentence is not in itself a finding about the gene and the disease.
cancer (continued). "Additionally, they produce NO and cytokines (interleukin-1β; IL-1β, interleukin-6; IL-6, interferon-γ; IFN-γ, and tumor necrosis factor-α; TNF-α), and these build up immune response and suppress the growth of cancer cells." (PMID 37107267, 2023). "This systematic review aims to assess whether the cytokines IL-6, IL-8 and TNF-α are potential salivary biomarkers that allow early diagnosis of cancer." (PMID 37099710, 2023). "In the case of cancer cells, the level of IL-6 for the dark control without PS was 1.00 pg/mL ± 0.18 pg/mL." (PMID 38258051, 2023). "A combination of CRP, IL‐6, YKL‐40, CEA and CA 19‐9 was the best predictor of cancer (AUC of 0.77)." (PMID 36440611, 2023). "In support of our data, a recent study showed a direct role for STING signaling in IL-6 production in response to the genotoxic treatment of cancer cells, independent of an IFN signature, biasing STING activity towards a pro-tumorigenic profile." (PMID 37176007, 2023). "In addition, crosstalk exists between TAMs and cancer cells in the TME, and IL-6 secreted by TAMs binds to the IL-6 receptor on the surface of cancer cells and phosphorylates STAT3 (pSTAT3)." (PMID 38074679, 2023). "CD44+/CD24−/low BCSC play a crucial role in cancer invasion, as cell lines with a higher proportion of CD44+/CD24−/low cells exhibit greater expression of pro-invasive genes, such as interleukin-1 alpha (IL1α), interleukin-6 (IL6), and interleukin-8 (IL8)." (PMID 37445860, 2023). "In line with previous reports, we could demonstrate that both IL-6 and IL-8 increased the mammosphere formation of MCF7 and MDA-MB-231 cells, suggesting a more malignant phenotype by an induction of cancer stem cell propagation." (PMID 38136303, 2023). "To explore the relationship between IL-6 and CTL in cancer patients, we selected patients from the IMmotion150 (RCC) and IMvigor210 (UC) trials with high (>10 pg/mL) or low plasma IL-6 and performed 10x single-cell RNA sequencing of their pre-treatment peripheral blood mononuclear cells." (PMID 36599350, 2023). "Furthermore, almost all cancers demonstrated a positive correlation between OAS1 expression and GSVA scores of the interferon-γ signaling pathway and IL6-JAK-STAT3 signaling pathway." (PMID 37928544, 2023). "Next, to identify the responsible factors activating NF-κB, we have treated cells (EP and LP) with MDSC supernatant in presence/absence of IL-6, IL-10 and IL-1β neutralizing antibodies, keeping untreated cancer cells as a control." (PMID 38304256, 2023). "Mechanistically, MAOA in stromal cells enhances IL-6 transcription and expression through Twist1 binding to an E-box element on the IL-6 promoter, which in turn activates paracrine IL-6/STAT3 signaling to transcriptionally upregulate the cancer stem cell marker CD44 in adjacent PC cells." (PMID 36860320, 2023). "Many pro-inflammatory cytokines, such as IL-1, IL-6, and TNF- α, are involved in regulating the production of albumin in hepatocytes, and they also play a particular role in regulating angiogenesis and cancer progression." (PMID 37197434, 2023). "Since IL-6/IL-8 is a component of the SASP, it is probable that the SASP may confer chemotherapeutic resistance by enhancing cancer-stem-cell-like properties." (PMID 36834846, 2023). "In the CRC-HSCs interplay, CRC promoted HSCs-to-CAFs differentiation by releasing vascular endothelial growth factor (VEGF); and HSCs released interleukin 6 (IL6) that activated signal transducer and activator of transcription 3 (STAT3) in the CRC and hence increased the cancer metastatic potential." (PMID 37062842, 2023). "Elevated IL-6 levels were also observed in patients without a family history of cancer (p = 0.012) and in those aged above 60 years (p = 0.048)." (PMID 38022654, 2023).
cancer (continued). "Through key components such as Oleanolic acid, Butin, β-sitosterol, Stigmasterol, and Enoxolone and other components interferes with AKT1, IL-6 and TNF, and regulates pathway in cancer, PI3K-AKt signaling pathway and MAPK pathway to play a therapeutic role in hepatitis E." (PMID 37035802, 2023). "Furthermore, the content of inflammation-related cytokines (interleukin-6 and CRP) was also significantly reduced in postoperative cancer patients." (PMID 37566134, 2023). "IL-6 is capable to convert non-stem cancer cells to cancer stem-like cells in breast and prostate cell lines." (PMID 37340387, 2023). "For this, we performed multicolor flow cytometry analysis and found that in the presence of neutralizing antibodies against IL-6 and/or G-CSF, or inhibition of MEK, the percentage of Ki67+ cancer cells was significantly reduced suggesting rescue from DTX induced dormancy outgrowth." (PMID 37699010, 2023). "We also investigated possible mediators of the cancer–stroma interplay that in OS may contribute to the modulation of ECM deposition and focused on IL-6." (PMID 36831562, 2023). "Cancer stage modified the association between randomized group and hs-CRP (P=0.022) and IL6 (P<0.001) but not sTNFαR2 (P=0.39)." (PMID 38148846, 2023). "Importantly, increased IL-6 levels positively correlate with disease progression and MDSC enrichment in cancer patients." (PMID 37006306, 2023). "It was shown that IL-6 activated gp130 leading to activation of the JAK/STAT pathway and the IL-6/JAK/STAT3 pathway is aberrantly hyperactivated in many types of cancer." (PMID 36911202, 2023). "Cancer cells release growth factors, such as FGF-2, VEGF, PDGF, EGF, TGFβ, and cytokines and chemokines, the core group consisting of CCL2, CCL5, IL-6, IL-8, as well as other soluble factors that activate fibroblasts and modulate CAF gene expression patterns and their metabolism." (PMID 37046676, 2023). "In addition, the expression levels of IL-6, IL-17, TNF-α,IL-12β, TLR-2, and TLR-4 as well as miR-21 and miR-31 showed a significant increase in the cancer group." (PMID 38075864, 2023). "However, it was reported that inflammatory cytokines which can alter levels of CYP expression (e.g., IL-6 reduction of CYP3A levels), resulted in a 28% decrease in midazolam metabolic intrinsic clearance in cancer patients following an oral dose." (PMID 37514108, 2023). "Moreover, STAT3 cooperates with NF-κB in IL-6 induction and the IL-6/STAT3 pathways synergize in the induction of c-MYC leading to promoting cancer cell survival." (PMID 37480115, 2023). "Furthermore, IL-6 and TGF-β initiate the epithelial-to-mesenchymal transition (EMT) process leading to cancer progression and metastasis." (PMID 37340387, 2023). "Carnitine can also decrease the elevated serum levels of IL-6 and TNF-α in cancer cachectic mice." (PMID 37600065, 2023). "In contrast, C0008 at the highest concentration resulted in a substantial release of TNFα, MCP-1, and IL6 from PBMCs without target cells at levels 3- to 5-fold lower than in the presence of target cancer cells." (PMID 37067909, 2023). "IL‐6 stimulates CRP secretion, regulates stromal desmoplasia, promotes tumour‐induced immunosuppression and angiogenesis, inhibits apoptosis, stimulates cancer cell proliferation and facilitates metastasis, including formation of a pro‐metastatic niche in the liver." (PMID 36440611, 2023). "Next, we identified significantly enriched KEGG (Pathways in cancer and PI3K/Akt signaling pathway) and GO (GO:0000122, GO:0045944 and GO:0045893) terms, and identified eight genes (EDN1, CCND1, MYB, MYC, RUNX1, ITGA6, IL6 and FGF2." (PMID 36978140, 2023). "Also, andrographolide has been shown to sensitize TNBC cells to doxorubicin via the downregulation of IL-6-mediated STAT3 phosphorylation, resulting in enhanced cancer cell cytotoxicity." (PMID 37570775, 2023).
cancer (continued). "In our study, we observed a significant increase in IL-6 secretion in HNSCCs with fibroblast co-cultures compared to cancer cell monocultures with or without irradiation." (PMID 37371868, 2023). "Moreover, blocking of IL-6 increased NK cytotoxicity to HCC cells through the inhibited expression of STAT3 and HIF-1α in cancer cells." (PMID 37501379, 2023). "The analysis revealed that the IL-6 levels in each cancer type were not significantly different between different anesthesia groups." (PMID 37345096, 2023). "•IL-6 confers adaptive and metastatic phenotypes on NK-LAAO-treated cancer cells." (PMID 37385076, 2023). "It is noteworthy that this effect of adenosine on inducing IL‐6 expression has been reported in immune cells but not in cancer cells previously." (PMID 37278400, 2023). "But a limitation of this explorative study of the diagnostic utility of plasma CRP, IL‐6 and YKL‐40 in detection of cancer is the lack of a validation cohort." (PMID 36440611, 2023). "ICAFs tend to secrete immune-relevant cytokines (e.g., IL-6, IL-11 and leukemia inhibitory factor, CXCL1, and CXCL2), which may promote cancer progression, migration, and chemoresistance." (PMID 37627173, 2023). "Certain systemic inflammatory markers, such as C-reactive protein (CRP), tumor necrosis factor alpha (TNF-α), interleukin-6 (IL-6), neutrophil-to-lymphocyte ratio (NLR), and platelet-to-lymphocyte ratio, are known to play a prognostic role in various types of cancer following surgery." (PMID 38137474, 2023). "The IL-6/JAK/STAT3 pathway plays a key role in the growth and development of many human cancers." (PMID 36839713, 2023). "The present work establishes a role of IL-6/ERK signaling in promoting M2-like macrophage polarization, and suggests this axis as a potential therapeutic target for combination with IFN-I-based cancer treatments." (PMID 36726024, 2023). "Hence, these findings confirmed that docetaxel alters IL-6 and G-CSF signaling by stromal cells in vivo augmenting MAP2K signaling in cancer cells, thus likely awakening cancer dormancy and promoting cell proliferation." (PMID 37699010, 2023). "Moreover, inflammatory cytokines such as IL-1 and IL-6 can induce the production of angiogenic factors like VEGF, while TNFα has the potential to promotes cancer cell proliferation, invasion, and metastasis, as well as tumor angiogenesis." (PMID 37006300, 2023). "IL-6 releases into TME and may be involved in cancer progression, immunosuppression, and the responses of cancer cells to chemotherapy and immunotherapy." (PMID 37480115, 2023). "MAPK10, FOS, and IL-6 genes show extensive low expression in LUSC, BRAC, KICH, and other cancers." (PMID 37666853, 2023). "Herein, a significant increase in IL-1β, IL-6, and TNF-α serum levels was detected that could support the role of proinflammatory cytokines in cancer patients." (PMID 37068081, 2023). "The obtained results are a good starting point for further studies on the cytoprotective role of IL-6 and MCP-1 against HNSCCs, first in 2D and 3D in vitro models, based on an in vivo model, designing an appropriate anti-cancer therapy combined with radiotherapy." (PMID 37371868, 2023). "Thus, IL-6 indirectly led, through FGF-2 stimulation, to increased NK sensitivity against the cancer cells, showing another possible new role for IL-6 in innate immunity against HCC." (PMID 37892997, 2023). "Disrupting IL-6 paracrine signaling of can inhibit the activity of BCR/ABL, and IL-6 inhibitors combined with PD-1 inhibitors can have an antitumor effect, thus contributing to the clearance of cancer cells in the CML TME." (PMID 36761742, 2023).
cancer (continued). "Moreover, the combination of IL-6 and TNFR2+ Tregs achieved an excellent predictive ability (AUC 1.000) in identifying patients with malignant tumors, and this was superior to AUC values for CA125 and HE4 (AUC value ranges 0.986–0.997)." (PMID 36765633, 2023). "Our results revealed that angiogenin down-regulated the secretion of IL-6, IL-8 and MCP-1 pro-inflammatory molecules by cancer cells, suggesting angiogenin could inhibit the inflammation." (PMID 38025776, 2023). "Following cancer cell death, several cytokines (i.e., IL-1, IL-6, IL-8, IL-12, IL-18) and chemokines such as CCL5 are released that lead to the mobilization and activation of additional immune cells, further contributing to the host’s defense against cancer." (PMID 37371127, 2023). "Notably, VEGF-A, TNF-α, CCL2, IL-6, and IFN-γ were significantly elevated in the Cancer TIF1-γ-DM group than in the Non-cancer TIF1-γ-DM group." (PMID 36357631, 2023). "DDIAS is also involved in homologous recombination DNA repair and IL-6/STAT3 signaling activation, which may contribute to cancer progression." (PMID 35681031, 2022). "Given the fact that IL-6 was one of the most induced cytokines in the context of cancer immunotherapy (ICB and adoptive therapy), we wanted to evaluate whether the IL-6/STAT3 axis could in fact be upregulating SMG1." (PMID 36443756, 2022). "Adipose tissue dysregulation promotes an inflammatory state in which adipocytes and immune cells release pro-inflammatory cytokines and sex hormones, such as hs-CRP, IL-6, leptin, TNF-α, estrogens, among others, increasing cell proliferation and cancer development." (PMID 35795051, 2022). "Our findings suggest that salivary IL-6, IL-10, and TNF levels may be used as biomarkers for OM occurrence and grade in patients with cancer." (PMID 35476641, 2022). "Interestingly, and besides IFN‐γ, estrogen deprivation also induced the secretion of IL‐6, which is a central inflammatory cytokine that stimulates JAK/STAT signaling and that is known to decrease the effectiveness of cancer immunotherapy." (PMID 34392603, 2022). "In addition, the regulators up- and downstream of IL6, namely, STAT3 and Toll-like receptors, respectively, have been successfully targeted in resistant cancer models." (PMID 35196078, 2022). "Among them, IL-6/janus kinase 2 (JAK2)/signal transducer and activator of transcription 3 (STAT3) signaling pathways may play a key role in the development of malignant tumors, participating in the entire process of invasion and metastasis." (PMID 36591515, 2022). "The development of cancer is usually accompanied by inflammation and cancer development and metastasis can be inhibited by treating or controlling inflammation and blocking the production of related factors (e.g., TNF-α, IL-6, IL-17, etc.)." (PMID 36686662, 2022). "Because CAF and TAM are known to modulate disease progression, we can expect that targeting cytokine and chemokine (e.g., CXCL, IL-6, and TGF-β) secretion by CAF could improve anti-cancer efficiency." (PMID 35159126, 2022). "Hypoxia and the HIF signaling pathway led to enrichment in CSCs, and curcumin/curcuminoid effects against cancer EMT are mediated through its action on this major tumor microenvironment factor, through a decrease in the expression of miR-21, miR-210, IL-6, HIF-1α, and VEGF." (PMID 35873564, 2022). "In particular, serum levels of interleukin-6 (IL-6) and tumor necrosis factor-α (TNF-α) may be increased as part of the host response to tissue damage or cancer treatments." (PMID 35331230, 2022). "The upregulation of IL-6 can amplify the metabolic cross-disorder STAT3 pathway between the two cells through the IL-6 signal, and CD36 has recently been shown to be a downstream target for activating STAT3, which will further promote fatty acid uptake of cancer cells." (PMID 36106333, 2022).
cancer (continued). "Some studies indicated that macrophages exposed to hypoxia/lactate may secrete IL-6, TNF-α, CCL5 and CCL18, which favor glycolysis and boost synthesis of pro-glycogenic factors in TME in some cancers." (PMID 36362348, 2022). "By secreting VEGF and IL-6, HNSCC cancer cells recruit macrophages and promote the M2 polarization." (PMID 36115852, 2022). "In cancer cells, HOTTIP was observed to bind to c-jun, inducing IL-6 expression." (PMID 36612180, 2022). "Thus, co-culture media, compared to MAT-MSCs and/or BC cell monoculture media had higher levels of IL-6, VEGF and IL-8; proteins involved in SASP; CAF functions and cancer aggressiveness." (PMID 36358839, 2022). "Accordingly, the cancer cells play a key role in neutrophil infiltration into TME by producing different signals including chemokines (e.g., IL-8, CCL2, CXCL6) and cytokines (e.g., IL-1β, IL-6, TNFα)." (PMID 36330498, 2022). "Curcumin has been shown to induce cancer cell autophagy by inhibiting the PKB/mammalian target of rapamycin (mTOR)/p70S6 pathway and MAPK1/2 pathway and inhibits signalling protein STAT3 by suppressing the IL6-mediated phosphorylation of STAT3." (PMID 35663647, 2022). "For instance, EVs derived from various cancer cell types, in addition to TGF-β, transfer tumor necrosis factor-α (TNF-α), interleukin 6 (IL-6) and matrix metalloproteinases (MMPs) to normal recipient cells, promoting their proliferation, migration and anchorage-independent growth." (PMID 35493080, 2022). "Our data highlight the key roles of this circRNA_101277/miR-370/IL-6 axis in the context of CRC chemoresistance and suggest that this pathway may be a viable target for the diagnosis and treatment of this deadly cancer type." (PMID 35356749, 2022). "Interestingly, IL-6 has been demonstrated to switch on the JAK/STAT3 pathway and enhance EMT, which in turn promotes cancer proliferation, metastasis, and chemoresistance." (PMID 35681689, 2022). "The CD163/IL‐6/Stat3 pathway is suggested to be critical in protumor TAMs, however, macrophage‐mediated cancer cell proliferation was not affected by anti‐IL‐6R antibody (unpublished data)." (PMID 35132816, 2022). "Interestingly, it was reported that the activated IL-6/JAK2/STAT3 pathway can inhibit bax/bcl2 related caspase-dependent apoptosis, leading to the promotion of proliferation and metastasis of cancer cells." (PMID 36431925, 2022). "Additionally, they stimulate cancer cell growth both directly, producing EGF, IL-6 and tumor necrosis factor (TNF), and indirectly, secreting pro-angiogenic factors." (PMID 35328686, 2022). "According to the content of IL-1β, IL-6, IL-8, IL-18, and IL-10, the subgroup of luminal B (HER2-positive) cancer differed from the rest of the luminal subtypes, which suggested that it was HER2 status that was the determining factor influencing on the content of cytokines in saliva." (PMID 36286034, 2022). "Here, we show that methylmalonic acid (MMA), an aging-increased oncometabolite also produced by aggressive cancer cells, activates fibroblasts in the TME, which reciprocally secrete IL-6 loaded extracellular vesicles (EVs) that drive cancer progression, drug resistance and metastasis." (PMID 36266345, 2022). "While IL-6 plays an important role in multiple physiological processes including cell proliferation, acute inflammation, and metabolism, active IL-6/JAK/STAT3 signaling drives cancer cell proliferation and invasiveness and suppresses apoptosis." (PMID 35565306, 2022). "This work shows that the compounds in GTF can play a role in bone protection by stably combining with IL6 and TGFB1, which may also be one of the reasons that GTF can prophylax and treat cancer-related pain." (PMID 35872837, 2022). "Moreover, in several cancers, including EAC, IL-6 induces epithelial-to-mesenchymal transition (EMT) by upregulating cancer stem cell associated genes." (PMID 35565378, 2022).